NFKB1 (nuclear factor kappa B subunit 1)
Diseases named in the same sentence as NFKB1 in open-access papers (continued):
Sharing a sentence is not in itself a finding about the gene and the disease.
tumor (continued). "Transcription factor (TF) activity prediction, using the DoRothEA resource, to identify potential regulons responsible for the signalling and phenotypes associated with HPS in HiFi tumours revealed a strong association with STAT1, STAT2, IFN (IRF1, IRF9) and NFκB (NFKB1, REL, RELA, RELB) TFs." (PMID 35477539, 2022). "Although the ranking order may vary, the majority of the top-ranked TEff/EM regulons such as Rora, Fosl2, Creb3, Maf, Prdm1, Nfil3, and Nfkb1 were also identified as top-ranked regulons for active TRMs in the tumor and distant mammary mucosa." (PMID 33979626, 2021). "However, NFKB1 is an inhibitor of inflammation and cancer and plays a tumor-inhibiting role by reducing abnormal activation of the NF-κB signaling pathway." (PMID 34794429, 2021). "The reason for the evident more rapid tumor growth in WT compared with p50(f/f) mice is uncertain but could reflect a mild effect of the loxP sites surrounding Nfkb1 exon 4 on p50 expression." (PMID 33480449, 2021). "The luciferase signal indicated that MCF7 cells infected with the NFKB1 shRNA initially formed tumours, but regressed over time; 6 weeks after injection, these tumours were smaller than those formed by the control MCF7 cells (uninfected or infected with turboRFP-control shRNA)." (PMID 28378740, 2017). "NFKB1 re-expression was found to partly abolish the tumor-suppressive effect of miR-508-3p in GC." (PMID 26801246, 2016). "Our data also demonstrates that NFκB p50 accumulation may be a mechanism of action of Mertk ligation and confirms both Mertk and NFκB1 p50 as potential target genes to improve tumor control to radiation therapy." (PMID 27602953, 2016). "In the tumor cells studied, Amblyomin-X blocked NFKB1 cleavage after proteasome inhibition, suggesting the inhibition of the NF-κB complex; thus, dynein function could not be related to its translocation to the nucleus." (PMID 25479096, 2014). "TNFA -308 or NFKB1 -94 ins/del polymorphisms did not modulate any site-specific risk of ESCC tumours." (PMID 24324738, 2013). "Moreover, overexpression of miR-9 led to suppressed cell proliferation and enhanced apoptosis together with downregulation of NFκB1 in I83-E95 cells, supporting a tumor suppressor role of miR-9-3 in CLL." (PMID 24373626, 2013). "Our results indicate that the NFKB1 -94 Ins promoter polymorphism increased the risk of HCC, and may be applied as a predictive factor for the clinical stage and tumor size in female HCC patients." (PMID 23457512, 2013). "miR-9-3 was a tumor suppressor miRNA hypermethylated in CLL, which was associated with down-regulation of NFκB1 protein, and hence might contribute to constitutive activation of NFκB signaling pathway in CLL." (PMID 24373626, 2013). "Together, these data support the hypothesis that tumor macrophage polarization limits the efficacy of radiation therapy, and demonstrate that expression of NFκB1 limits the efficacy of radiation therapy in vivo." (PMID 22761754, 2012). "There are also many experimental data suggests that NFκB1/IκB pathway may participate in tumor cell invasion as well." (PMID 21738780, 2011). "In addition, by targeting NFκB1, miR-9 could enhance the sensitivity of tumor cells to ionizing radiation." (PMID 32785098, 2020). "Functional blockade of NFKB in epidermal cells resulted in severe hyperplasia of the skin in the transgenic mice, and effect that could be reversed by the overexpression of active RELA and the NFKB1 subunit of NFKB, suggesting that NFKB has a tumor suppressive effect." (PMID 31363162, 2019). "In tumor samples, JUN exhibited significantly lower expression in MSC1 and MSC2 (P < 0.05), while NFKB1 was significantly reduced in MSC2 and MSC3 (P < 0.01)." (PMID 40666524, 2025). "MTDH promotes tumor proliferation by inhibiting transcriptional factor FOXO1 and activating MEK/ERK and NFκB1 pathways, thereby driving tumor progression." (PMID 40149331, 2025).
tumor (continued). "Immune evasion was evident through upregulation of NFKB1, IFNAR1, TLR4, IL1A/B/R1, and NOS2, facilitating tumour escape from immune surveillance." (PMID 41007296, 2025). "When focusing on regulatory patterns, we found that CAFs displayed distinct cell type-specific TFs alongside shared TFs widely involved in carcinogenesis, including various tumor promoters or tumor suppressors, such as KLF4, NFIA, TCF21, NFKB1, and EGR1." (PMID 39872221, 2025). "Further, expression levels of TF regulators in the NF-κB family (NFKB1, NFKB2, RELA, RELB) were highest in TS3 cluster, reinforcing the notion that NF-κB pathway activation within the tumor epithelium drives TS3." (PMID 39289380, 2024). "In the syngeneic PC model, IL30-targeting immunoliposomes downregulated NFKB1 expression and prevented intratumoral influx of CD11b+Gr-1+MDCs, Foxp3+Tregs, and NKp46+RORγt+ILC3, and prolonged host survival by inhibiting tumor progression." (PMID 39232121, 2024). "In GC, NFKB1 and HIF1A are dysregulated and often involved in tumour growth, proliferation, tumour-promoting inflammation, chemoresistance, and cell differentiation." (PMID 39816318, 2024). "Reduced NFKB1 in NFκB impedes SEC14L3 promoter and enhancer activation, forming a positive feedback loop that enhances tumor suppression." (PMID 39425205, 2024). "RELB, NFKB1, BCL3, and FOXO3, found in NEAT1+ tumor cells, were closely related to the CSCs phenotype." (PMID 37430270, 2023). "Evidently, knockdown of NFKB1 and RELA instigated an anti‐tumour effect by suppressing cell proliferation as evidenced by monolayer colony formation assay and by inhibiting cell invasion." (PMID 37983931, 2023). "Among the top 10 significantly correlated TFs with A3A RNA levels in bulk RNA-seq profiles, three TFs' (FOSL1, NFKB1 and VEZF1) expression levels were greatly different between tumor and normal tissues." (PMID 37215984, 2023). "NFKB1, NFKBIA, TNFRSF1A, and FASN were found to be related to DNA repair, which affects tumor sensitivity to DNA-damaging agents." (PMID 35899106, 2022). "Deletion of IL30 dramatically downregulated BCL2, NFKB1, STAT3, IGF1 and CXCL5, whereas tumor suppressors, primarily SOCS3, were upregulated." (PMID 36224639, 2022). "Of the transcriptional factors, CREB5, HIF1A, NFKB1, and PIK3CA, downregulation of NFKB1 and PIK3CA supports tumor growth and survival." (PMID 35967849, 2022). "This signaling pathway reduces cell death by altering the expression of genes involved in the apoptotic process such as BIM, NFκB1, NFκB2, AURKA, and AURKB, thereby increasing tumor growth." (PMID 36482411, 2022). "TAMs secrete cytokines (IL6, IL10, etc.)and exosomes (miR-21-5p, miR-155-5p, etc.)through NFKB1 signaling pathway, STAT3 signaling pathway, and other pathways to act on tumor cells and immune cells, regulating the process of CRC." (PMID 35186730, 2022). "As a subunit of NF-κB, NFKB1 has been shown to be a pathway-specific suppressor of inflammation, aging, and tumours such as hematological malignancies." (PMID 36601599, 2022). "In addition, the expression of key genes in the TNF-α/NF-κB signaling, including NFKB1 (p50), RelA (p65), TNFRSF1A (TNFR1), TNFR1-associated death domain protein (TRADD), and TNF receptor-associated factor 2 (TRAF2), was examined in the cell lines and tumor tissues of EBV-associated cancers." (PMID 35008199, 2021). "In fact, while CD4+ lymphocytes upregulate A20 and NFKB1 genes over-time when embedded in tumor 3D constructs, CD8+ lymphocytes immediately downregulate most NF-kB genes." (PMID 34070750, 2021).
tumor (continued). "Overexpression of miR-181a significantly decreased the expression and activity of crucial NF-κβ signaling components in DLBCL, leading to reduced tumor cell proliferation and survival by targeting CARD11, NFKB1A, NFKB1, RELA and REL." (PMID 34679437, 2021). "NFKB1 and RELA are biomarkers in NF-κB pathway, which has been reported to regulate tumor invasiveness." (PMID 34486492, 2021). "To investigate the role of TNF-α, we analyzed the association of the level of NF-κB p50 transcripts with the methylation status of the NFKB1 and the RELA genes in tumor tissues depending on the expression of TNF-α." (PMID 31382678, 2019). "nfκb1−/− mice develop chronic liver disease (CLD), characterized by the emergence of dysplastic nodules, fibrosis and increased tumour frequency." (PMID 30468013, 2019). "We previously demonstrated using a model of diethylnitrosamine (DEN)-induced HCC that Nfkb1−/− mice exhibited accelerated HCC and significantly increased tumour numbers compared to wild type mice." (PMID 30205516, 2018). "The Nfkb1−/− mice also show enhanced CXCL-10 chemokine expression and hence CD4+ and CD8+ T cell infiltration that help combat tumour growth in this model." (PMID 30205516, 2018). "Mechanically, evidence also showed that NFKB1 was a negative regulator of the NF-κB, which could upregulate expression of anti-apoptotic genes, such as IAPs, cell-cycle promoters, and growth factors and their receptors, further supporting its tumour suppressive role." (PMID 29484114, 2018). "These genes are known to be implicated in proliferation (MAPK8), metastatic diffusion of tumor cells (ITGB1), drug resistance (ANXA1), coagulation (ANXA3, ANXA5) or inflammation (HPGD, NFKB1)." (PMID 29228619, 2017). "NFKB1-positive tumors were more likely to be found in elder age group (P = 0.052), but RELA-positive tumor are strongly correlated with N stage (P = 0.042)." (PMID 26801246, 2016). "To further confirm that p50 K146ac contributed to the antitumor immune function of ACAT1 pS60, we induced Acat1-Flag WT or S58D expression in Nfkb1-depleted CT26 cells rescued with HA-mp50 (1-364aa) WT or K144R (equivalent to K146R in humans) and performed subcutaneous tumor model." (PMID 40289129, 2025). "In exploring tumor cell signatures linked to ICI response, non-responder attributes were regulated by STAT3 and NFKB1." (PMID 39514276, 2024). "Tumour infiltrating lymphocyte and myeloid populations were enriched for motifs including ETS family transcription factors (ETV5/6 and EHF) and MEF2B, as well as NFKB1 which is a central activator of pro-inflammatory genes." (PMID 39341888, 2024). "We found that MAP2K6, MAP3K5, MAP3K9, MAP3K12, RPS6KA2, RPS6KA5, and STAT1 were lowly expressed in tumor tissues; However, NFKB1, RAC1, SHC1, and TRAF2 are highly expressed compared to normal tissues." (PMID 36969076, 2023). "In GC, NFKB1, NFKB2, REL, RELA, and RELB were significantly upregulated in tumor tissues." (PMID 35036435, 2022). "In addition, CYCS and NFKB1 presented low expression, while IKBKB and TRADD presented high expression in TCGA and clinical tumor samples." (PMID 35502302, 2022). "Similarly, reduced inflammatory regulator NFKB1 and increased negative regulator CAT indicated that KMV stimulation prevented macrophage polarizing into inflammatory tumor suppressive phenotype, which is in line with our previous qPCR results." (PMID 36311795, 2022). "Consequently, the pathway is like a bridge to connect tumor and TAMs, and TAMs have been proved to be involved in many pathways important to CRC,namely, NFKB1 pathway, STAT3 pathway, WNT5A pathway, and PI3K pathway." (PMID 35186730, 2022).
tumor (continued). "Compared to normal samples, although MAIT cells reduced in HCC, tumor-derived MAIT cells down-regulated genes enriched in the cytokine secretion and cytolytic effect pathways (NFKB1 and STAT5B) and up-regulated genes such as IL8, CXCL12 and HAVCR2 (TIM -3) promote tumor development." (PMID 33574818, 2020). "When Nfkb1−/− mice are implanted with murine fibrosarcoma there is no observed defect in M1 cytokine production and tumour growth is significantly reduced." (PMID 30205516, 2018). "For example, the silencing of miR-9-3a tumor suppressor miRNA by methylation may account for the constitutive upregulation of NFKB1, and hence the constitutive activation of NF-κB in CLL patients." (PMID 28561798, 2017). "However, both NFKB1 and RELA protein expression showed up-regulated in tumor samples compared with paired normal gastric tissues after quantified normalization (P = 0.004 and P = 0.012 respectively)." (PMID 26801246, 2016). "Both NFKB1 and RELA were mainly localized in the cytoplasm of the tumor cells." (PMID 26801246, 2016). "The most significant, predicted activated upstream regulators in OS-2 (worse prognosis), relative to OS-1 tumor xenografts, were CEBPB and NFKB1 (P-value 5.54E–10 and 3.94E–09, respectively), whereas the most significant predicted inhibited upstream regulator was MEF2C (P-value 2.54E–23)." (PMID 27874835, 2016). "The effect of NFKB1 and RELA expression on in vivo tumor growth was also studied." (PMID 26801246, 2016). "An absence of Nfkb1 had the least impact on the phenotype observed in wild‐type mice, with similar numbers and sizes of tumours being observed following AOM/DSS administration." (PMID 25727407, 2015). "As expected, we confirmed in individual tumor samples of our patients an inverse correlation of these target mRNA and miR-107 expression levels, being this correlation significant for CCND1, DICER1, DROSHA and NFKB1." (PMID 25197016, 2014). "Consistent with this, we noticed considerable changes in co-expression for several NFκB complexes including the NFκB1/REL family, which plays important roles in programmed cell death and proliferation control and is critical in tumour initiation and progression." (PMID 25521701, 2014). "NFKB1 mRNA levels were significantly lower in morphologically normal tissues 1 and 2 from cancer patients, and tumour tissue (P<0.001 for all) compared to healthy individuals." (PMID 23977225, 2013). "There were 748 NF-κB targets predicted and individually annotated for RELA, NFκB1 or cREL regulation, and a prevalence of RELA related genes was observed in over-expressed clusters in a tumor subset." (PMID 18334025, 2008). "Interestingly, PD-1 and NFKB1 also demonstrated significant negative correlations with tumor size, however, the strength of these two correlations was weaker compared Ltb." (PMID 39623404, 2024). "At this time point, NFKB2 and RelA genes were strongly reduced in both healthy and tumor conditions (NFKB2 in h3D vs. 2D p = 0.023; t3D vs. 2D p = 0.014; RelA in h3D vs. 2D p = 0.020; t3D vs. 2D p = 0.006), while the t3D samples also downregulated NFKB1 (p < 0.001)." (PMID 34070750, 2021). "Indeed, MCP-1 and IL-8 are transcriptional targets of NFKB1 and RELA in tumor cells." (PMID 29928478, 2018). "In addition, the expression of miR-508-3p showed negative correlation with NFKB1 protein expression in tumor tissues and NFKB1 re-expression partly abolished the inhibitory effect of miR-508-3p in GC." (PMID 26801246, 2016). "Thus, our in vivo data support the notion that metronomic TPT induces senescence in a MNA NB model without up-regulation of NFKB1/p50 and production of a tumor-promoting SASP." (PMID 26657295, 2016).
tumor (continued). "Therefore, it is not surprising that NFKB1 acts as a tumour promoter in this context." (PMID 30205516, 2018). "Lack of NF-κB subunit Nfkb1 in PSCs reduces CXC12 secretion, increases infiltration of CD8+ T cells, inhibits tumor growth, and improves host survival, evaluated by orthotopic co-injection experiments with primary tumor cells from KPC mice and PSCs." (PMID 35159011, 2022). "Intriguingly, Pladienolide-B did not influence the expression of genes relevant to tumor biology (apoptosis, proliferation, inflammation) in MIAPaCa-2 cells or in HPDE E6E7 cells, including NFKB1, CASP3, MKI67, and HER2." (PMID 34857016, 2021). "In addition, NF-κB family members such as transcription factor Rel B and NFκB1 are elevated to a greater extent in IBC tumor tissue when compared to non-IBD, implying that NF-κB is constitutively active in IBC." (PMID 29874851, 2018).